PTX3 (pentraxin 3)
Diseases named in the same sentence as PTX3 in open-access papers (continued):
Sharing a sentence is not in itself a finding about the gene and the disease.
acute myocardial infarction (continued). "The aim of this study was to measure serum pentraxin 3 (PTX3) in patients with acute myocardial infarction (MI) and compare it with the control group." (PMID 34306119, 2021). "Increased levels of PTX3 were reported in patients with systemic inflammation, including septic shock, myocardial infarction, and systemic vasculitis." (PMID 34208590, 2021). "According to its dual role, the cardioprotective function of PTX3 has been demonstrated in acute myocardial infarction." (PMID 32508664, 2020). "In other clinical conditions such as myocardial infarction, PTX3 peaked in less than 12 h, whereas the CRP level peaked after 24 h after admission to the hospital." (PMID 32372340, 2020). "Several lines of investigation support PTX3 as a useful biomarker of inflammation under a wide range of clinical conditions, including acute myocardial infarction, atherosclerotic lesion, rheumatoid arthritis, and septic shock." (PMID 31316299, 2019). "Data collected so far indicate that PTX3 plasma levels rise rapidly in acute myocardial infarction, heart failure and cardiac arrest, reflecting the extent of tissue damage and predicting the risk of mortality." (PMID 31057548, 2019). "Particularly in the field of sterile inflammation, IL-1 is a potent inducer of PTX3 production during tissue damage, as occurs in mouse models of acute myocardial infarction (AMI)." (PMID 31354697, 2019). "In this regard, increased levels of PTX3 is observed in vascular disorders, such as myocardial infarction and small vessel vasculitis that correlate with worsen outcome or disease activity." (PMID 31354697, 2019). "In our study, some of the maximally dysregulated mRNAs, including Il6 and Ptx3 were directly related with myocardial infarction." (PMID 31827539, 2019). "The long pentraxin PTX3 is expressed in the heart under inflammatory conditions and has a cardioprotective role in acute myocardial infarction in mice." (PMID 29416668, 2018). "We used a PTX3 concentration of 10 ng/mL because this is the reported concentration level in human blood when inflammation occurs, such as during acute myocardial infarction." (PMID 28955836, 2016). "In particular, plasma level of PTX3 increases in patients with acute myocardial infarction (AMI) after about 7 h from the onset of symptoms, with a decrease at baseline levels after three days." (PMID 27559355, 2016). "Although knowledge about circulating PTX3 levels during acute myocardial infarctions has increased lately, data on protein levels in relation to the genetic mRNA levels have until now been scarce." (PMID 24737925, 2014). "Higher circulating PTX3 levels in AMI patients compared with those in the AP patients short time after PCI indicate that the myocardial infarction per se somehow influences PTX3 levels." (PMID 24737925, 2014). "Another possibility is that neutrophil activation leading to PTX3 release precedes the myocardial infarction or is partially responsible for the plaque rupture." (PMID 24737925, 2014). "Systemic detection of PTX3 has been of prognostic value as observed in acute myocardial infarction, predicts adverse clinical outcome in patients with heart failure and is associated with coronary plaque vulnerability and furthermore decreased by statins." (PMID 24060373, 2013). "PTX3 is present in the intact myocardium, increases in the blood of patients with acute myocardial infarction, and represent an early indicator of myocytes irreversible injury in ischemic cardiomyopathy." (PMID 23690668, 2013). "Following myocardial infarction (MI), PTX3 plasma levels peak within 7.5 hours as compared to CRP which peaks around 50 hours." (PMID 23690668, 2013). "Following myocardial infarction, increased PTX3 mRNA and protein expression was observed in the ischemic area of the heart." (PMID 23690668, 2013).
acute myocardial infarction (continued). "Due to the prominent role in the crossroad between innate immunity, ECM deposition and vascular biology, PTX3 serum levels have been assessed in a variety of diseases including vasculitis, myocardial infarction and systemic inflammation." (PMID 23516586, 2013). "In alignment with our data, PTX3 plasma concentrations were shown to be increased in patients with acute myocardial infarction and were therefore suggested as an early indicator for infarction and irreversible injury of the myocyte in ischemic cardiomyopathy." (PMID 21048961, 2010). "However, direct evidence of PTX-3 and IL-6 modulation by butylphthalide in myocardial infarction models remains limited, warranting further investigation." (PMID 41281269, 2025). "PTX3 is proven to be an independent prognostic factor for cardiovascular risk, independent of CRP levels, with studies reporting high plasma levels of PTX3 in patients with myocardial infarction or carotid stenosis." (PMID 36553147, 2022). "However, in acute myocardial infarction as well as in myocarditis, increased PTX3 expression of both macrophages and endothelial cells was found." (PMID 32508664, 2020). "Using an experimental model of myocardial infarction and samples of myocardial infarction of patients, Maugeri and coworkers demonstrated that neutrophils were the main source of increased PTX3 in blood of patients with AMI in the early phase of the symptoms (within 6 h)." (PMID 31354697, 2019). "Peri and coworkers demonstrated that plasma levels of PTX3 were elevated after myocardial infarction faster than C-reactive protein, suggesting that PTX3 could be used as an earlier indication of cardiac IRI." (PMID 31354697, 2019). "For instance, plasma PTX3 levels rise during early acute myocardial infarction." (PMID 28955836, 2016). "In 2000 it was reported that PTX3 increases during acute inflammation in patients suffering from acute myocardial infarction, and for this reason PTX3 is considered to be a new biochemical marker in acute myocardial infarction, along with troponin and creatine kinase." (PMID 26903710, 2016). "We propose that PTX3 could be a new treatment for acute inflammation, especially in macrophage-related wounds, such as following myocardial infarction, in atherosclerotic lesions, and in systemic inflammation in which macrophages participate." (PMID 28955836, 2016). "The PTX3 level might serve as an early indicator of myocardial infarction and thus reflects the atherosclerotic activity." (PMID 27559483, 2016). "Once released, PTX3 inhibits both local P-selectin-dependent leukocyte enrollment on endothelial cells and platelet aggregation, presumably in order to dampen the inflammatory process and the subsequent injury of an acute myocardial infarction." (PMID 24737925, 2014). "Pentraxin3 (PTX3) is a protein, which has multifaceted effects on innate immunity, angiogenesis, and vascular remodeling then could be a disease marker of acute myocardial infarction, heart failure, vasculitis." (PMID 25412085, 2014). "Increased blood PTX3 levels have been associated with infection severity, prognosis of patients with acute myocardial infarctions, activation of autoreactive T cells, psoriatic skin inflammation, and severity of acute respiratory distress syndrome, which suggests that PTX3 mediates inflammation." (PMID 23383162, 2013). "In addition, in humans, PTX3 plasma levels increase during vascular atherosclerosis, inflammation, or damage especially after myocardial infarction and reach the peak much earlier compared to CRP." (PMID 23690668, 2013). "The PTX3 plasma concentration is increased in patients with acute myocardial infarction." (PMID 23248627, 2012).
acute myocardial infarction (continued). "Given the abundance of neutrophils both in the circulation and in the inflammatory foci, these cells whose life-span has been prolonged into the bargain constitute the main source of PTX3 right after the onset of infection or in acute sterile inflammation, such as myocardial infarction." (PMID 22577258, 2012). "In a subsample of the Cardiovascular Health Study, baseline PTX3 was associated with cardiovascular and all cause mortality, yet not with incident angina or myocardial infarction." (PMID 22319633, 2012). "PTX3 is also described as an early indicator of acute myocardial infarction (AMI) in humans and its cardioprotective role, by modulating the reperfusion-associated inflammatory response and tissue damage, is dependent on the IL-1RI pathway, as determined in a mouse model of AMI." (PMID 20920344, 2010). "In addition, a cardio-protective effect has also been reported for PTX3 in murine models of acute myocardial infarction, and increased plasma levels and cardiac expressions of IL-6 and generation of ROS have been shown in the ischemic myocardium of PTX3-knock out animals." (PMID 36362273, 2022). "Similarly, a prognostic value of PTX3 has also been demonstrated in myocardial infarction or CAD." (PMID 35888704, 2022). "In addition, considering the local production and the rapid change in plasma concentration, PTX3 could be considered a novel potential biomarker of myocardial infarction." (PMID 27559355, 2016). "Plasma concentration of PTX3 rapidly rises in the early phase after ischemic heart disorders in humans and animal models suggesting the possibility that PTX3 could also play a role in myocardial infarction." (PMID 23690668, 2013). "Pentraxin-3 (PTX3) is an acute-phase protein known to exert anti-inflammatory and protective effects in peripheral inflammatory conditions including infection, acute myocardial infarction and lung inflammation (see for review)." (PMID 31602423, 2019). "In the model of myocardial infarction in mice, induction of ischemia resulted in upregulation of PTX3 production, an effect almost completely absent in il-1r1- or myd88-deficient mice." (PMID 31057548, 2019). "Elevated circulating PTX3 levels shortly after PCI in AMI patients compared to AP patients indicate that the myocardial infarction per se influences PTX3, although the levels were not correlated to infarct size." (PMID 24737925, 2014). "In patients with acute myocardial infarction (AMI), PTX3 peaked in plasma sooner than CRP, 6–8 h from symptom onset and, when measured with established markers including CRP, NT-proBNP and troponin-T, emerged as the only independent predictor of three-month mortality." (PMID 23285251, 2012). "Alberto Mantovani's team furthermore evidenced that in genetically modified mice, PTX3 plays a protective role in acute myocardial infarction, notably in the reperfusion phase." (PMID 22577258, 2012). "Recent studies have shown that PTX3 has a nonredundant regulatory and cardioprotective role in acute myocardial infarction in mice." (PMID 21876831, 2011). "In a large cohort of patients with myocardial infarction, with ST elevation, PTX3 but not the liver-derived short pentraxin CRP or other cardiac biomarkers (NT-proBNP, TnT, CK) predicted 3-month mortality after adjustment for major risk factors and other acute-phase prognostic markers." (PMID 23690668, 2013). "It is tempting to speculate that comparable effects of PTX3 would be operative in patients with myocardial infarction, but reliable proofs thereof are as yet lacking." (PMID 22577258, 2012). "PTX3 plasma levels are also increased in some non-infectious conditions that involve inflammation and endothelial damage, such as vascular atherosclerosis, inflammation or vascular damage, especially after myocardial infarction, reflecting the extent of tissue damage." (PMID 32244987, 2020).
endothelial dysfunction (62 papers, 2013 to 2026). In vascular diseases, endothelial dysfunction is a systemic pathological state of the endothelium (the inner lining of blood vessels) and can be broadly defined as an imbalance between vasodilating and vasoconstricting substances produced by (or acting on) the endothelium. "In DN, elevated PTX3 levels are associated with glomerular inflammation, endothelial dysfunction, and kidney injury." (PMID 40299501, 2025). "PTX3 is associated with endothelial dysfunction suppressing cell proliferation or reducing nitric oxide synthesis." (PMID 37941784, 2023). "Increased levels of plasma PTX3 were associated with the clearance of apoptotic cells by dendritic cells resulting from high immune response and endothelial dysfunction in cardiovascular disorders." (PMID 35204613, 2022). "Our study shows that serum ADMA, MDA, PTX3 levels are associated with endothelial dysfunction in patients with selected chronic diseases." (PMID 32488098, 2020). "PTX3 was associated with proteinuria and endothelial dysfunction in patients with advanced CKD or type 2 diabetes, suggesting that PTX3 is more than just an additional marker of inflammation in chronic HF." (PMID 31057548, 2019). "High plasma PTX3 levels are associated with many human diseases related to endothelial dysfunction, including chronic kidney disease, preeclampsia, and hypertension-related multisystem complications." (PMID 31780874, 2019). "PTX3 is elevated in dialysis patients compared to healthy controls and reflects endothelial dysfunction associated with CVD and mortality risk." (PMID 30277113, 2018). "Pentraxin-3 has been associated with endothelial dysfunction, decreased eGFR, and proteinuria in previous studies." (PMID 29783932, 2018). "Plasma PTX3 is considered as an inflammatory marker of endothelial dysfunction and is also linked to increasing cardiovascular mortality risk." (PMID 30277113, 2018). "On this regard, high plasma levels of the inflammatory molecule PTX3 were associated with endothelial dysfunction in different human diseases." (PMID 27559355, 2016). "Patients with chronic kidney diseases and with preeclampsia, a multisystemic disorder associated with hypertension, show elevated PTX3 plasma levels which were correlated with the severity of endothelial dysfunction." (PMID 27559355, 2016). "Our finding corroborates previously reported associations between elevated PTX3 and surrogate markers of endothelial dysfunction." (PMID 23658833, 2013). "Moreover, PTX3 is associated with endothelial dysfunction and vascular inflammation and serves as a biomarker of endothelial damage during chronic migraine." (PMID 38743922, 2024). "PTX3 might be implicated in PAH pathogenesis through inflammation, endothelial dysfunction, along with cardiac functional alternations in maintenance hemodialysis patients, and PTX3 could serve as a hallmark for screening PAH." (PMID 37773724, 2023). "Furthermore, a recent study found that, PTX3 caused endothelial dysfunction and damaged vascular system by inducing inflammatory response and metabolic changes of endothelial cells." (PMID 31957804, 2020). "Considering that our exclusion criteria eliminated these confounders, it is tempting to postulate that high levels of PTX3 and sTWEAK are a result of pathophysiologic mechanisms related to migraine rather than a consequence of other conditions associated with endothelial dysfunction." (PMID 32244987, 2020). "Based on these data, PTX3 could be considered as a novel biomarker for hypertension and a new target for future therapeutic strategy aimed to contain endothelial dysfunction and associated CVD." (PMID 27559355, 2016). "PTX3 levels, together with proteinuria, were also shown to be independently associated with endothelial dysfunction in end-stage renal disease patients; this suggests the possibility that PTX3 could also represent a biomarker of peripheral vascular damage." (PMID 23690668, 2013).
endothelial dysfunction (continued). "Longitudinal profiling demonstrated that endothelial dysfunction emerges early, with PTX3 showing the strongest and most rapid upregulation in hospitalized patients, supporting its potential role as a marker of imminent vascular involvement." (PMID 41929307, 2026). "PTX-3 is a promising biomarker for myocardial injury, reflecting local inflammation, endothelial dysfunction and the extent of cardiac damage." (PMID 39941683, 2025). "In this context, Pentraxin 3 (PTX3)—an acute-phase protein produced by myeloid and endothelial cells—has emerged as a potential biomarker of inflammatory activity, endothelial dysfunction, and disease prognosis." (PMID 41471254, 2025). "Nonetheless, our findings confirm those of previous studies reporting that PTX‐3 is a more sensitive marker of endothelial dysfunction compared to CRP." (PMID 39414396, 2024). "On one hand, thyroid hormones, along with PTX3 and, insulin resistance share common mechanisms in the development of endothelial dysfunction, a vascular pathophysiological genetically driven mechanism of migraine." (PMID 36797674, 2023). "Recently, pentraxin 3 (PTX3) arises as a new sensitive marker of endothelial dysfunction in PCOs patients." (PMID 33917519, 2021). "Highly significant positive correlations were shown between serum galectin-3 concentrations and the studied inflammatory markers, including IL-6, PTX-3, and ferritin, and the endothelial dysfunction marker, sFlt-1." (PMID 34439802, 2021). "On the other hand, potential damaging effects have been ascribed to PTX3 due to its capacity to induce endothelial dysfunction, exacerbated complement activation and inflammation." (PMID 33679758, 2021). "PTX-3 decreases nitrogen oxide synthesis in endothelial cells, reducing cell proliferation and function and thus promoting endothelial dysfunction." (PMID 32670996, 2020). "ADMA, MDA and PTX-3 were the markers responsible for the improvement of endothelial dysfunction in patients using these three products with anti-inflammatory, anti-oxidant and anti-atherosclerotic properties." (PMID 32488098, 2020). "Some biomarkers related with TGV activation, such as CGRP or endothelial dysfunction, such as pentraxin-3 (PTX3), have recently been described as predictors of good response to OnabotA in CM (measured in peripheral blood during interictal periods)." (PMID 32731573, 2020). "These evidences are in accordance with data provided from several labs describing PTX3 as a biomarker of endothelial dysfunctions, regulating nitric oxide, P-selectin, and fibroblast growth factor-2 production." (PMID 32508664, 2020). "Carrizzo and coworkers have shown that PTX3 promotes endothelial dysfunction and morphological changes by a mechanism dependent on P-selectin and matrix metalloproteinase-1 (MMP1) pathway." (PMID 31354697, 2019). "In the recent studies, the concentration of plasma PTX3 has been reported as a close and independent determinant of proteinuria, impaired kidney function, and endothelial dysfunction." (PMID 29725602, 2018). "The lack of significant rises in vascular biomarkers (sVCAM-1, vWf, and PTX3) with increasing disease activity in our patients with RA may suggest that the presence of RA itself-rather than the magnitude of concomitant inflammatory activity-underlies endothelial dysfunction." (PMID 24864133, 2014). "Recently, a study has demonstrated that PTX3 is expressed in adipose tissue, and its tissue specific expression reflects endothelial dysfunction." (PMID 24350299, 2013). "In conclusion, this study shows that increased SAT PTX3 mRNA expression is associated with increased circulating PTX3, higher ADMA levels and endothelial dysfunction in the uremic milieu." (PMID 23658833, 2013).